WT1 (WT1 transcription factor)
Diseases named in the same sentence as WT1 in open-access papers (continued):
Sharing a sentence is not in itself a finding about the gene and the disease.
tumor (continued). "Another trial is investigating the use of galinpepimut-S vaccine (a WT1 analog peptide vaccine) in combination with pembrolizumab in multiple tumor types including SCLC (NCT 3761914)." (PMID 32766139, 2020). "Immunohistochemistry showed that the tumor cells were positive for WT1 (strong and diffuse nuclear and cytoplasmic), caldesmon, CD99 (cytoplasmic, not membranous), S100 (subset), and SMA (subset)." (PMID 32490123, 2020). "It has been demonstrated that Wilms' tumor suppressor WT1 is a major regulator of tumor neovascularization and tumor progression." (PMID 32855630, 2020). "Among our samples, WT1 was detected in the cytoplasm, astrocytic processes and fibrillary tumor matrix with infrequently, concomitant nuclear expression." (PMID 32856872, 2020). "The tumor of origin of patient 3392 tests positive for Napsin A, and tests negative for estrogen receptor (ER), progesterone receptor (PR), WT1, and ARID1A, suggesting that the tumor was not of endometrial origin." (PMID 32784519, 2020). "Dendritic cells were found to take up apoptotic WT1-expressing tumor cells, and present the WT1332 peptide on their cell surface in association with HLA class II molecules." (PMID 30430205, 2019). "We show that, in tumor endothelium, Wt1, Srpk1, and Srsf1 are upregulated compared to normal lung endothelium." (PMID 30641926, 2019). "In nine patients who had an increased level of the WT1 tumor marker at the start of DC therapy, WT1 transcript levels returned to normal during DC vaccination, compatible with the induction of complete molecular remission (CMR)." (PMID 31035598, 2019). "Nuclear BASP1 participates in gene regulation converting the Wilms tumor transcription factor WT1 from an oncoprotein into a tumor suppressor." (PMID 31058089, 2019). "VEGF transcription during tumor growth is stimulated by hypoxia, which is mediated via hypoxia inducible factor 1 (Hif-1) and the Wilms’ tumor suppressor 1 (Wt1)." (PMID 30641926, 2019). "Techniques for concomitant membrane and nuclear staining are not sufficiently optimised yet to show how many of these are also WT1+ to confirm that these are tumour cells." (PMID 31319587, 2019). "For instance, the tumor suppressor genes WT1 and PI3KR1 were hypermethylated and underexpressed in high E-score tumors whereas RUNX1 and PBRM1 were hypermethylated and underexpressed in high S-score tumors." (PMID 30902996, 2019). "For WT1, the tumor cells showed strong nuclear staining with an antibody recognizing the C-terminal region of WT1 (C-WT1) (polyclonal, Abnova)." (PMID 31103034, 2019). "CXCR4-A-armed virotherapy followed by FL-mediated expansion of CD103+ DCs prior to vaccination was most effective in inhibiting tumor growth (median survival of 69 days) and inducing WT1-2Db/RMFPNAPYL tetramer+CD8+ TILs." (PMID 31384667, 2019). "Wt1, Srpk1, Srsf1, and the angiogenic VEGF164a isoform were highly expressed in tumor endothelium compared to normal lung endothelium." (PMID 30641926, 2019). "As demonstrated here, intratumoral accumulation of CD103+ DC populations at the tumor site served as a platform for the adjuvanted WT1-specific peptide vaccine booster, leading to generation of WT1 tetramer+CD8+ TILs and increases in overall survival." (PMID 31384667, 2019). "After that, however, he had recurrence near the original tumor 1 year and 9 months after the WT1 vaccination." (PMID 30430205, 2019). "This tumor was found to lack 5′-regional expression of the WT1 gene, as well as immunoreactivity with the N-WT1 antibody." (PMID 31103034, 2019). "We show here that Wt1, Srpk1, Srsf1, and the angiogenic Vegf 164a isoform are highly expressed in tumor endothelial cells compared to normal lung endothelium." (PMID 30641926, 2019). "In a recent novel study, a T-cell receptor-mimic (TCRm) CAR, known as WT1-28z, responded to a peptide portion of the intracellular antigen WT1, as it is presented on the surface of the tumour cell in the context of HLA-A*02:01." (PMID 30678059, 2019).
tumor (continued). "This confirms that WT1 is indeed a broadly expressed tumor antigen and a suitable target for active specific immunotherapy, also in pediatric cancer patients." (PMID 31546858, 2019). "On the other hand, ligand conjugated WT1-shRNA reduces 34% of tumor weight with prolonged survival rate." (PMID 29861465, 2018). "Patient Wilms10 with a tumor‐specific homozygous WT1 deletion within a heterozygous 11p13 deletion and a tumor‐derived cell line (Wilms10T) have been reported." (PMID 29542868, 2018). "Only CD4+ T cells among the tumor infiltrating CD45.1+ immune cells were statistically higher in mice treated with the WT1 combination vaccine than in those treated with the WT1 CTL vaccine alone." (PMID 30542516, 2018). "Frequencies of WT1 tetramer+ CD8+ T cells were measured in tumor cell suspension that was made by disassembling the tumors." (PMID 30542516, 2018). "In a certain mouse treated with the combination vaccine, WT1-specific CD8+ T cells accounted for up to as much as 26.9% of tumor infiltrating CD8+ T cells." (PMID 30542516, 2018). "High rate of expression of WT1 and their significant role as a prognostic factor makes WT1 mRNA an ideal tumor marker for leukemic blast cells as well as a potential target for RNAi mediated gene therapy for various cancer treatments." (PMID 29861465, 2018). "The number of WT1 tetramer+ CD8+ T cells per 1 × 105 tumor cells were also significantly higher in the tumors of mice treated with the WT1 combination vaccine than in those of mice treated with the WT1 CTL vaccine alone." (PMID 30542516, 2018). "Like p16, the expression of WT1 is low in DIPG tumor samples compared to NBS-HGG samples with wild type H3.3." (PMID 29932419, 2018). "After adjusting for age and tumour subtype, the hazard ratio for WT1 expression was 2.17 (p = 0.0589)." (PMID 30057405, 2018). "Other tumor suppressor genes, such as WT1, SMAD4, and BRCA2, which are also silenced in all samples, are frequently associated to polycomb-repressed (E15, H3K27me3) or heterochromatin-like (E12, H3K9me3) states." (PMID 29773832, 2018). "Transferrin (Tf), a glycoproteins over expressed on the surface of the cancer cells was used as a ligand to carry WT1-shRNA to tumor." (PMID 29861465, 2018). "In summary, WT1 plays key role in leukemogenesis and tumorigenesis as an oncogene but it was originally known as a tumor suppressor gene." (PMID 29861465, 2018). "One explanation is the increased infiltration of the WT1-specific effector CD8+ T cells via enhancement by WT1-specific CD4+ T cells of their homing into the tumor from outside." (PMID 30542516, 2018). "The total numbers of WT1-positive cells, CD31-positive cells, and WT1/CD31 dual-positive cells were all higher in Grade I tumours." (PMID 30374123, 2018). "The total number of WT1+ cells was increased in the triple-negative cancers versus tumour-free sections from matched controls." (PMID 30374123, 2018). "Since this malignancy is a very heterogeneous disease and the WT1 locus is extremely complex, we started our study with a comprehensive assessment of WT1 expression in the different tumour subtypes followed by an isoform specific expression analysis." (PMID 28345629, 2017). "Distribution ≥50% of MSLN-, CA125-, and WT1-positive tumor cells were observed in 84%, 20%, and 72% of epithelioid MPM cases, respectively." (PMID 29100432, 2017). "As a novel identified oncogene, WT1 was found overexpressed in human HCC compared with non-tumour liver, and its high expression correlates with low overall survival." (PMID 29285297, 2017). "We then selected representative tumours from triphasic, epithelial-predominant, and stromal-predominant (WT1-mutant) groups for double immunofluorescence." (PMID 29040332, 2017).
tumor (continued). "Analyses of WT1 expression in different human cancers already indicate the involvement of this transcription factor in tumour development and progression." (PMID 28107196, 2017). "WT1 is a nuclear protein that is involved in tumor growth and overexpressed in multiple malignancies." (PMID 29100432, 2017). "Seeded on Matrigel, HOSEpiC developed into spheres whereas PDCLs formed morphologically diverse “cancer organoids” that expressed the tumour markers CA‐125 and WT1." (PMID 29180611, 2017). "Our results suggest that the targeting of WT1 is an important mechanism by which the tumor-suppressive function of miR-193a is exerted." (PMID 29016617, 2017). "Expression of the genes encoding WT1, survivin and TERT is used as a prognostic marker, and these TAAs have been characterized as powerful tumor antigens in AML." (PMID 28477011, 2017). "The capacity of IL-15 designer DC to present tumor-specific antigen was assessed in an HLA-restricted WT1-specific T-cell model." (PMID 28785596, 2017). "It is composed of the N-terminal domain of the EWS gene and of the C-terminal DNA binding domain of the WT1 tumor suppressor gene." (PMID 28166781, 2017). "In conclusion, more than two-thirds of MPM patients have ≥50% distribution of MSLN-positive cells within whole tumor cells and, among the remaining one-third, half have ≥50% distribution of WT1-positive cells." (PMID 29100432, 2017). "BASP1 is a direct target of miR-191; BASP1 inhibition by miR-191 leads to transactivation of WT1, which activates the Wnt pathway to promote tumor progression." (PMID 29089860, 2017). "A previous study has demonstrated that WT1 plays an important role in the pathogenesis of this tumor by inducing primitive neuroblastic cells to differentiate into mature less malignant ganglion cells." (PMID 27014421, 2016). "WT1, a well-studied tumor suppressor has dual roles in cancer progression depending on the presence or absence of regulatory protein partners." (PMID 26590405, 2016). "This is further supported by our previous description of a patient with a germ line WT1 mutation who developed four tumors with different CTNNB1 mutations, suggesting their independent origin and/or tumor heterogeneity." (PMID 27213811, 2016). "For example, FOXD1 is typically expressed in stromal cells and also in all WT1 mutant tumor derived cell lines we have established previously." (PMID 27213811, 2016). "Multiple-ligation probe analysis (MLPA,) did not identify copy number variations in the blood DNA, whereas the tumor DNA carried a homozygous deletion of the WT1 gene." (PMID 27213811, 2016). "Neuroblatoma is traditionally considered as a WT1-negative tumor, but a few studies have shown a variable (often focal and weak) nuclear and/or cytoplasmic expression of WT1 in this tumor." (PMID 27014421, 2016). "Inhibition of WT1 in solid cancers and hematological malignancies demonstrates potential anti-tumor activities." (PMID 27821145, 2016). "The primary Wilms10 tumor cells show a limited multilineage differentiation potential for osteogenesis, adipogenesis and muscle differentiation, similar to the other WT1 mutant cells." (PMID 27213811, 2016). "Array based-comparative genomic hybridization (a-CGH) confirmed the tumor had numerous chromosome copy number losses, including 11p15.5-p11.12 and 22q12.1-q13.33, with loss of the EWSR1 and WT1 gene regions." (PMID 27403364, 2016). "This indicates that the patient had a tumor specific homozygous WT1 deletion and a heterozygous deletion extending at least to the HIPK3 gene." (PMID 27213811, 2016). "WT1 functions are complex, including activation and repression of transcription and oncogenic and tumor-suppressor properties." (PMID 27197573, 2016). "Equally, the post-MET/early tubulogenesis block found in the Pax8+/CreWt1co kidneys more resembles the epithelial nature of WT1-wild-type tumours." (PMID 26035382, 2015).
tumor (continued). "Immunohistochemical staining showed that most tumour cells were positive for WT-1, CD57, MIB-1, Vimentin, and EMA, while CK7 staining showed weak focal positivity." (PMID 25907695, 2015). "We found the prognostic value of WT1 requires the presence of tumor-infiltrating CD3+ T cells: the WT1 antigen appeared with a strong stimulatory effect (for nearly 70% of patients, 9-10 months of improved PFS when co-expressing high levels of CD3)." (PMID 26622942, 2015). "WT1 RNA expression levels were analyzed by real-time quantitative PCR (RT-qPCR) in 15 SCCHN tumor specimens, 7 adjacent tumor-free tissue samples and 14 normal control tissues of the tongue." (PMID 25929687, 2015). "Enrichment for epigenetic modifier functions (green nodes), especially H3K4 and H3K9 methylation, is uniquely found in the WT1-wild-type tumours." (PMID 26035382, 2015). "Although tumours with this combination of genetic aberrations can be found in patients, phenotypically they are closer to the WT1-wild-type subset than the WT1/β-catenin mutant tumours." (PMID 26035382, 2015). "Using immunohistochemistry, we performed WT1 protein staining in 90 formalin-fixed tumour samples and found that only 5 out of 90 samples showed positive staining in cytoplasm." (PMID 25929687, 2015). "We compared a published microarray dataset of WT1-mutant and WT1-wild-type tumours to the Nes-Cre Wt1 conditional and Pax8+/CreWt1 conditional datasets." (PMID 26035382, 2015). "Prior studies with the protein BASP1 showed that N-myristoylation and PIP2 recruitment to nuclear speckle domains plays an important function in the transcriptional repression of the Wilm’s Tumor gene (WT1)." (PMID 26470026, 2015). "As reported in Case presentation section the tumor cells were diffusely positive for calretinin and CK 8/18 and focally positive for CK 5/6, WT1, e-cadherin, and HBME-1." (PMID 25849448, 2015). "The authors suggested an intermediate mesoderm origin for the WT1-mutant tumours and a metanephric mesenchyme origin for the WT1-wild-type cases." (PMID 26035382, 2015). "If our interpretation of the Nes-Cre- and Pax8+/Cre-driven Wt1 mutants and how they compare to WT1-mutant and WT1-wild-type tumours is correct, our data also highlights other differences between these two tumour groups." (PMID 26035382, 2015). "Immunohistochemical analysis showed tumor cells diffusely positive for cytokeratin (CK) 8/18 and calretinin and focally positive for CK 5/6 and Wilms’ tumor 1 (WT1), e-cadherin, and human bone marrow endothelial- 1 (HBME-1)." (PMID 25849448, 2015). "Accordingly, the WT1 wild-type and mutant subsets of tumours can clearly be recognized using genome-wide expression analysis." (PMID 26035382, 2015). "MTOR-inhibitors were found to downregulate the expression of the EWS/WT1 transcript and increase the Bax/BcL-xL ratio resulting in increased tumor cell death." (PMID 25945075, 2015). "Analysis of the AIRE promoter region using rVista 2.0 indicated a predicted TFBS for WT1 (Wilms Tumour 1) at this position with the predicted binding site immediately downstream of -230Y." (PMID 25978041, 2015). "This approach, when used to target more broadly expressed tumor antigens such as WT-1 and additional Cancer-Testis antigens will enhance the scope and feasibility of adoptive T cell therapy." (PMID 25317334, 2014). "Wilms tumor 1 (WT1) is over-expressed in numerous cancers with respect to normal cells, and has either a tumor suppressor or oncogenic role depending on cellular context." (PMID 24405639, 2014). "We have recently demonstrated that WT1 can act as a tumor suppressor in clear cell renal cell carcinoma (ccRCC) regulating hTERT gene expression via multiple pathways." (PMID 24715586, 2014).
tumor (continued). "Our data identifies MMP9 as a novel WT1 target gene and demonstrates that WT1 expression directly regulates tumor growth through a global effect on angiogenesis." (PMID 24810959, 2014). "In particular, we evaluated the expression of PTEN, WT1 and IL-6 receptor (p80, gp130) genes, as they act as tumor suppressors and signal transducers." (PMID 24731550, 2014). "WT-1 expression was found to be immunohistochemically positive in TLFCK tumor cell nuclei, indicating that these tumors originate in the kidneys." (PMID 24932236, 2014). "Suppressed tumor growth, decrease in the amount of cancer cells, and reduced level of tumor marker have been reported as effects of WT1 peptide postvaccination 42–47." (PMID 24715586, 2014). "Suppression of WT1 in MHH-ES cells profoundly slows tumor growth, while exogenous WT1 increases the growth of SK-ES-1 xenografts." (PMID 24810959, 2014). "Despite its tumor suppressor function, WT1 prevents programmed cell death in some cell types but promotes it in others." (PMID 25491731, 2014). "Recent studies have suggested that WT1 has an important role not only as a tumor suppressor, but also as a tumor promoter in various kinds of neoplasm." (PMID 25026998, 2014). "Specific staining for WT1 was observed in the cytoplasm of tumor cells, but in a few cases, both cytoplasmic and nuclear staining was observed." (PMID 25026998, 2014). "Early study by using antisense oligonucleotides has showed that WT1 is required not only for proliferation but also for inhibiting apoptosis in tumor cell cultures." (PMID 24667279, 2014). "WT1 is a tumor antigen over-expressed in several types of tumors and one of the top antigens currently explored for cancer immunotherapy." (PMID 28548069, 2014). "WT1 involvement in human cancer is very complex, acting as a tumor suppressor in some contexts and as an oncogene in others." (PMID 25474318, 2014). "Conclusively, these findings indicate that WT1 promotes growth of tumor in vivo and also depends upon up-regulation of the expression of Cyclin D1 and p-pRb." (PMID 23936312, 2013). "Immunohistochemically, the tumor shows positivities of WT-1 and CD57, similar to metanephric tumors." (PMID 24083046, 2013). "We selected 5 CpG loci with significant methylation differences by tumor histology (q-value < 2.2E-16 and fold-change > 2.50) for validation by Pyrosequencing (HOXA9_E252_R, SOX1_P294_F, WT1_E32_F, WNT2_P217_F, MDR1_seq_42_S300_R)." (PMID 23806198, 2013). "Mice vaccinated with WT1 plasmid DNA elicited CTLs against the WT1 protein, and the CTLs specifically killed WT1-expressing tumor cells in a MHC class I-restricted manner." (PMID 23394714, 2013). "Comparable number of WT1 SNP genotypes in 78 ccRCC tumour and corresponding tumour-free renal cortical tissue pairs." (PMID 23484026, 2013). "WT1 RNA expressions were analyzed by RQ-PCR in a total of 115 tissue samples including 100 tumour and 15 tumour-free specimens." (PMID 23484026, 2013). "Of these 9 patients, 4 had received intratumoral DC vaccine and 3 (75%) showed PR or SD, while in the remaining 2 patients exhibiting disease control, the antigens for DCs were a tumor lysate and WT1+MUC1, respectively." (PMID 24649223, 2013). "We recently demonstrated that Wilms’ tumor 1 (WT1) mRNA-electroporated LCs are superior to moDCs as stimulators of tumor antigen-specific CD8+ CTLs, even though they are comparable stimulators of allogeneic T cell proliferative responses." (PMID 23837662, 2013). "We have previously demonstrated that WT1 can act as a tumour suppressor in RCC via multiple pathways leading to down-regulation of hTERT." (PMID 23484026, 2013). "The genotypes of WT1 SNPs in 78 tumour-free kidney tissue specimens were found to be in 95% concordance with corresponding tumour samples." (PMID 23484026, 2013).